WDR81 (WD repeat domain 81)
Description:
Functions as a negative regulator of the PI3 kinase/PI3K activity associated with endosomal membranes via BECN1, a core subunit of the PI3K complex. By modifying the phosphatidylinositol 3-phosphate/PtdInsP3 content of endosomal membranes may regulate endosome fusion, recycling, sorting and early to late endosome transport. It is for instance, required for the delivery of cargos like BST2/tetherin from early to late endosome and thereby participates indirectly to their degradation by the lysosome. May also play a role in aggrephagy, the macroautophagic degradation of ubiquitinated protein aggregates. In this process, may regulate the interaction of SQSTM1 with ubiquitinated proteins and also recruit MAP1LC3C. May also be involved in maintenance of normal mitochondrial structure and organization (By similarity).
Synonyms: FLJ33817; PPP1R166; CAMRQ2; SORF-2; CHMRQ; HYC3
Tractability: Antibody: UniProt places it where antibodies can reach, with high confidence. PROTAC: ubiquitination databases record sites on it; its protein half-life has been measured.
Gene: Protein-coding gene on chromosome 17 (1,716,523 to 1,738,599, forward strand). Ensembl gene ENSG00000167716.
Subcellular location: Early endosome membrane; Late endosome membrane; Lysosome membrane; Cytoplasmic vesicle, autophagosome membrane; Mitochondrion; Cytoplasm, cytosol
Subcellular location (Human Protein Atlas): Nucleoplasm; Cytosol; Vesicles
Pathways (Reactome):
Signal Transduction: CDC42 GTPase cycle
Gene Ontology:
Molecular function: K63-linked polyubiquitin modification-dependent protein binding; phosphatidylinositol 3-kinase inhibitor activity; protein binding; phosphatidylinositol 3-kinase regulator activity
Biological process: aggrephagy; early endosome to late endosome transport; protein stabilization; ubiquitin-dependent protein catabolic process; mitochondrion organization
Cellular component: autophagosome membrane; cytosol; early endosome membrane; endoplasmic reticulum membrane; endosome membrane; Golgi apparatus; late endosome membrane; lysosomal membrane; mitochondrion
Genetic constraint (gnomAD): Loss-of-function variants: 92 observed, 133.93 expected, observed/expected ratio (o/e) 0.69, 90% interval 0.58 to 0.82. The upper end of that interval is the gene's LOEUF score, 0.82, which puts it in group 3 of 6, group 1 being the genes least tolerant of losing a copy. Missense variants: 2,502 observed, 2,604.9 expected, observed/expected ratio (o/e) 0.96, 90% interval 0.93 to 0.99. Synonymous variants: 1,183 observed, 1,148.6 expected, observed/expected ratio (o/e) 1.03, 90% interval 0.98 to 1.08.
Homologues: Orthologues: chimpanzee WDR81 (99% identical), macaque WDR81 (97% identical), pig WDR81 (91% identical), dog WDR81 (90% identical), rabbit WDR81 (90% identical), guinea pig WDR81 (89% identical), mouse Wdr81 (88% identical), rat Wdr81 (87% identical), zebrafish wdr81 (56% identical), tropical clawed frog wdr81 (55% identical), Drosophila melanogaster Wdr81 (31% identical). Paralogues in human: NWD1 (12% identical), TEP1 (9% identical), COP1 (9% identical), WDR62 (8% identical), MAPKBP1 (7% identical), WDR7 (5% identical), AHI1 (5% identical), WDR17 (5% identical), WDR27 (4% identical), WDR75 (4% identical), DAW1 (4% identical), NEDD1 (4% identical), and 14 more.